ULBP2 (UL16 binding protein 2)
Diseases named in the same sentence as ULBP2 in open-access papers (continued):
Sharing a sentence is not in itself a finding about the gene and the disease.
tumor (continued). "Interestingly, complete tumor regression was observed with anti-CTLA-4 antibody therapy, even in ULBP2-expressing tumors, suggesting that immune suppression induced by ULBP2 can be overcome under certain conditions." (PMID 40558520, 2025). "Preclinically, the STING agonist cGAMP both directly activates NK cells and sensitizes PDAC cells (e.g., ULBP2/5/6 upregulation and apoptosis), and, in combination with mesothelin-targeted CAR-NK-92, achieves superior tumor control and prolongs survival in mouse models." (PMID 40940881, 2025). "Compared to the negative control group, tumor growth was inhibited in the ULBP2 knockdown group, particularly after irradiation." (PMID 40640957, 2025). "We showed that ULBP2 CAR-T cells effectively eliminated GC cell lines and organoids and, either alone or in combination with an anti-PD-1 antibody, significantly inhibited tumor growth and prolonged survival in both CDX and PDX mouse models." (PMID 40775202, 2025). "Therefore, ULBP2 CAR-T cells alone strongly inhibit GC growth and prolong survival, and the anti-tumor effects are further augmented when combined with PD-1 blockade." (PMID 40775202, 2025). "In contrast, anti-CTLA-4 antibody treatment induced marked tumor regression irrespective of ULBP2 expression." (PMID 40558520, 2025). "In the present study, CD8+ T cell depletion experiments did not provide direct evidence that ULBP2 suppresses CD8+ T cell-mediated anti-tumor immunity." (PMID 40243581, 2025). "In conclusion, our study demonstrates that surface-expressed ULBP2, but not soluble ULBP2, plays a critical role in tumor progression by modulating NKG2D-mediated immune responses." (PMID 40243581, 2025). "Therefore, soluble NKG2DLs levels are expected to be markers of tumor progression and prognosis, because soluble MICA and ULBP-2 levels distinguish significantly between benign and malignant disease, both in solid organ cancers and in hematopoietic cancers." (PMID 37674990, 2022). "Supernatant of tumor cells treated with CaP-NPs was collected for measurement by ELISA and cells were analyzed by flow cytometry to determine expression of tumor cell stress ligand MIC-A, ULBP-2,5,6, MHCI and CD54." (PMID 35251021, 2022). "They analyzed GSC derived from primary tumor samples by mass cytometry, and the GSC expressed normal levels of NK cell activation receptor ligands (ULBP2, ULBP3, VIM) and upregulated levels of NK cell inhibitory receptor ligands (HLA-A, HLA-B, HLA-C, HLA-E, HLA-G, PCNA) compared with non-GSC." (PMID 34638384, 2021). "On the other hand, tumor-directed recombinant ligands that engage NKG2D may also enhance tumor cell targeting, as recently documented against malignant B cells for bispecifics composed of CD20-binding and NKG2D ligand (MICA or ULBP2) domains." (PMID 29740448, 2018). "Furthermore, miR-519a-3p impaired tumor cell killing by natural killer (NK) cells via downregulation of the NKG2D ligands ULBP2 and MICA on the surface of tumor cells that are crucial for the recognition of these tumor cells by NK cells." (PMID 28771222, 2017). "Besides myeloid cells, NK cells potentially can be activated by DNA damage-induced upregulation of UL16 binding protein 2 (ULBP2), a natural killer group 2D (NKG2D) ligand, which greatly enhance NK-mediated tumor elimination." (PMID 27869779, 2016). "A second human DNA damage response NKG2D ligand, ULBP2, was induced in the metronomic CPA-treated U251 tumors, but only at day 18, suggesting that MICB, and not ULBP2, contributes to the early onset of U251 tumor regression following metronomic CPA treatment." (PMID 25952672, 2015). "ULBP2 on the tumor cell surface can bind to NKG2D receptors on immune cells, such as NK cells and CD8+ T cells, ultimately inducing the innate immune response of killing and scavenging tumor cells." (PMID 25295097, 2014).
tumor (continued). "In contrast to NK cell-induced shedding of ULBP2 on apoptotic cells, the spontaneous shedding of ULBP2, albeit at a lower level, occurs on non-apoptotic tumor cells." (PMID 24614922, 2014). "Here we show, for the first time, that human tumor cells lost their surface expression of ULBP2, but not ULBP1 and ULBP3, during NK cell-mediated cytolysis." (PMID 24614922, 2014). "Serum BIGH3 and ULBP2 levels were not statistically correlated with age, gender, histological grade, overall tumor stage, or TNM classification of PC in this case-control study." (PMID 21625447, 2011). "It has recently been proposed that proteolytic shedding of ULBP2 from tumor cells is mediated by matrix metalloproteases (MMP), and may impair the immunogenicity of tumor cells." (PMID 21625447, 2011). "In contrast, soluble ULBP2 did not significantly affect tumor growth or immune responses." (PMID 40243581, 2025). "Nevertheless, the study suggests that surface-expressed ULBP2 may not consistently influence tumor elimination across all stages of tumor development." (PMID 40243581, 2025). "Furthermore, IGF2BP3 diminishes the ability of natural killer cells to recognize transformed cells by downregulating the stress-induced ligands UL16 binding protein 2 (ULBP2) and major histocompatibility complex class I polypeptide-related sequence B (MICB), contributing to tumor immune evasion." (PMID 37554271, 2023). "In addition to PD-L1 upregulation, suppression of NK group 2D (NKG2D)-activating ligands (including ULBP1, ULBP2, ULBP3, MHC class I chain-related molecules A and B, MICA and MICB) may represent another way of tumor escape from NKCC." (PMID 34830209, 2021). "The tumor cell lines (MDA-MB-453, THP-1, RH30, RH41, TE671, A204, Renca-lacZ, Renca-lacZ/erbB-2), peripheral blood mononuclear cells (PBMCs) and the primary aRMS VJ cells were analyzed for the expression of the NKG2D ligands ULBP-2/5/6, and MIC A/B, as well as for the expression of ErbB2 (HER2/neu)." (PMID 29029499, 2017). "Meanwhile, serum levels of ULBP2 was positively correlated with ADAM10 expression shown by immunohistochemistry, suggesting that gemcitabine may exerts its anti-tumor effect through inhibition of ADAM10 mediated ULBP2 shedding and corresponding enhanced NKG2D-mediated tumor elimination." (PMID 27602753, 2016). "Thus, approximately 50% of the samples had high MICA expression on a high percentage of tumor cells and most samples had no ULBP-2 expression." (PMID 23626949, 2013). "First, human ULBP2, a human NKG2D ligand not endogenously expressed in mice, was ectopically introduced into murine tumor cells." (PMID 40558520, 2025). "The immunohistochemical scores of both proteins in tumor tissues were statistically higher than those in non-cancerous counterparts: 0.54±0.46 versus 0.14±0.27 for BIGH3 (p<0.0001) and 2.71±0.49 versus 1.89±0.74 for ULBP2 (p<0.0001)." (PMID 21625447, 2011). "We then evaluated the suitability of ULBP2 as an early detection marker of PC by testing serum ULBP2 levels in patients with early-stage primary tumors (TNM-T1/T2), no lymph node metastasis (TNM-N0), and at early overall tumor stages (stage I–II)." (PMID 21625447, 2011).
cancer (50 papers, 2009 to 2025). A tumor composed of atypical neoplastic, often pleomorphic cells that invade other tissues. "ULBP2 promotes the formation of a dense stromal microenvironment in GC by activating cancer-associated fibroblasts (CAFs) and driving collagen deposition through the TGF-β signalling pathway." (PMID 40775202, 2025). "Elevated serum levels of soluble ULBP2 have been reported to be associated with poor prognosis in patients with cancer." (PMID 40558520, 2025). "In cancer, the loss of ULBP2 leads to reduced NK cell-mediated cytotoxicity and cytokine production." (PMID 31100862, 2019). "Similarly, analyses of NanoString PanCancer Immune Profiling data from multiple studies covering ten cancer types revealed ULBP2 as part of an immune gene signature associated with shorter overall survival in both solid and blood malignancies." (PMID 40243581, 2025). "ULBP2 is associated with poor prognosis in patients with cancer based on clinical data." (PMID 40243581, 2025). "Moreover, pan-cancer patients from the high-risk group apparently had high expression of NK cell ligands, such as ULBP2." (PMID 35813478, 2022). "The diagnostic and prognostic values of ULBP2 in cancer were reported in a lot of previous studies." (PMID 33909599, 2021). "Enhanced expression of ULBP2 on cancer cells leads to more efficient elimination of these cells by NK cells." (PMID 39963142, 2025). "Previous study demonstrated that ULBP2 has been reported to be epigenetically suppressed in various cancers." (PMID 40551137, 2025). "Recent comprehensive analyses of immune-related genes, using the Cancer Genome Atlas datasets and NanoString PanCancer Immune Profiling data, have identified ULBP2 as one of the top poor prognostic factors in both solid and hematopoietic malignancies." (PMID 40243581, 2025). "CCK-8 assays demonstrated that knockdown of ULBP2 significantly impaired the proliferative capacity of cancer cells (all p<0.01)." (PMID 40496857, 2025). "Apart from the IRE1α axis, the PERK–ATF4–CHOP pathway upregulates explicitly the expression of NKG2DL (mainly MICA and ULBP2) in cancer cells, enhancing their binding to NKG2D and subsequently activating NK cells for cancer cell destruction." (PMID 40547943, 2025). "UL16-binding protein 2 (ULBP2) is constantly expressed or elevated in cancer cells and serves as an important NKG2D ligand." (PMID 40940831, 2025). "Our findings suggest that targeting the persistent interaction between NKG2D and surface-expressed ULBP2 on cancer cells offers a promising therapeutic approach." (PMID 40243581, 2025). "UL16-binding protein 2 (ULBP2), always expressed or elevated on cancer cells, functions as a key NKG2D ligand." (PMID 39963142, 2025). "The overexpression of ULBP2 in tumors and its pleiotropic roles in cancer progression make it an attractive therapeutic target." (PMID 40775202, 2025). "The expression of the NK cell receptor ligand ULBP2 is increased in cancer compared to precancers and controls (p < 0.0001)." (PMID 39672307, 2024). "In squamous cell carcinoma only, individuals with higher ULBP2 expression had poorer survival, showing that cancer cells with more potent immune evading properties lead to a worse prognosis for patients." (PMID 39672307, 2024). "At the same time, we found that patients with high expression of ULBP2/3 in tonisil cancer had a poor prognosis, whereas high expression of ULBP1 was unrelated to prognosis." (PMID 37565867, 2023). "In a similar study in colon cancer, a cross-reactive recombinant immunoligand was fused with human ULBP2 and an antibody-derived single chain that binds to carcinoembryonic antigen on the surface of cancer cells." (PMID 36305981, 2022). "A previous study confirmed that the soluble ULBP2 secreted by cancer cells contributed to the immune escape." (PMID 35938006, 2022).
cancer (continued). "Among them ADAM10, a catalytically active member of the ADAM family of proteases, is involved in the cleavage of MICA, MICB, and ULBP-2 molecules in various types of cancer cells." (PMID 32269567, 2020). "Among them, ADAM10 cleaves MICA, MICB, and ULBP-2 in different types of cancer cells and its increased expression correlates with cancer progression in MM, malignant pleural mesothelioma, oral squamous cell carcinoma, and gastric cancer." (PMID 32570952, 2020). "Our results showed that strong cell-surface expression (2+ and 3+) of MICA and ULBP2 was detected in about 68 and 72% of the cancer tissues, respectively." (PMID 31288857, 2019). "MicroRNAs (miRNA or miR) were the first molecules described to impair the expression of the NKG2D ligands MICA, MICB and ULBP2 in cancer cells on mRNA level." (PMID 30254634, 2018). "Using a cutoff value of 60 pg/mL for ULBP2, we found that the sensitivity and specificity values for cancer detection were 83.8% and 73.9%, respectively." (PMID 21625447, 2011). "Meanwhile, the serum levels of ULBP2 among all PC patients (n = 154) and in early-stage cancer patients were significantly higher than those in healthy controls (p<0.0001)." (PMID 21625447, 2011). "This suggests that the variants present in the associated signals may alter not only RAET1L expression but also ULBP1, ULBP2, and ULBP3 and affect the risk of cancer and immune diseases." (PMID 40116579, 2025). "Considering the critical role that ULBP2 plays in facilitating cancer cell elimination by NK cells and the immune-modulatory effects exerted by RES, the current research aimed to elucidate the impact of RES on ULBP2 expression and the underlying molecular mechanisms involved." (PMID 39963142, 2025). "In addition to the suppression of T-cells, our data on the expression of ULBP2 and HLA-E shows that inhibition of NK cells also drives progression from precancer to cancer." (PMID 39672307, 2024). "ULBP2, a ligand of NKG2D, is associated with poor prognosis in a number of human cancers, and surface expression of this protein is often lost in many human cancer cell types during NK cell-mediated cytolysis." (PMID 32756008, 2020). "As a result, better understanding the mechanism of shedding of ULBP2 may facilitate the development of ULBP2-based diagnosis methods for cancers." (PMID 24614922, 2014). "Moreover, the functions of ectopically expressed ULBP2 may differ from those of endogenously expressed ULBP2 in human cancer cells." (PMID 40243581, 2025). "Also ULBP1 biogenesis in cancer cells is critically affected by RBPs, as is ULBP2 mRNA stability." (PMID 30254634, 2018). "Hence, a marker panel that combined CA 19-9 with other useful markers, such as ULBP2, could enhance the ability to detect and monitor cancer." (PMID 21625447, 2011). "The binding of ULBP2 and NKG2D initiates NK cell activation and the subsequent targeted elimination of cancer cells." (PMID 40940831, 2025). "The T cell markers CD28 and FLT3LG expression decreased in cancer while FOXP3, IDO1, and ULBP2 expression increased." (PMID 39672307, 2024). "TAP1 was abundantly expressed across all cell clusters, ULBP2 was primarily expressed in T cells, CXCL1 was mainly expressed in CAFs, myeloid cells, normal epithelial cells, and cancer epithelial cells." (PMID 39020010, 2024). "UL16 binding protein 2 (ULBP2) is expressed on cancer cells and binds to the natural killer (NK) cell activating ligand, NKG2D, increasing cancer cell sensitivity to NK cell-mediated cytotoxicity." (PMID 39170516, 2024). "In adult cancer patients, plasma levels of soluble MICA and ULBP2 proteins are elevated and have been shown to inhibit NK function." (PMID 39310750, 2024). "Our pediatric cancer patients had lower plasma concentrations of soluble MICA and ULBP2 than their healthy age matched counterparts excluding this as a possible explanation for the reduced K562 killing we observed." (PMID 39310750, 2024).
cancer (continued). "They used the immunoligand fused with the NKG2D-specific ligand ULBP2 to activate the receptor NKG2D and obtained high anticancer efficacy in the mouse model by inhibiting tumor development in vitro and by increasing cancer cell lysis." (PMID 36305981, 2022). "It downregulates the ligands for NKG2D, UL16 binding protein 2 (ULBP2), and MHC-I related chain A (MICA), on the surface of cancer cells leading to obstructed recognition by NK cells." (PMID 35053449, 2022). "This exosome-mediated immunosuppressive phenotype has also been observed in prostate cancer cells where cancer cell-derived exosomes containing MICA/B, ULBP1, or ULBP2 led to the downregulation of NKG2D receptor expression on effector populations." (PMID 35565467, 2022). "Cancer cells express NKG2D ligands, including UL16-binding protein 2 (ULBP2), which bind to the receptor present on NK cells." (PMID 33171792, 2020). "The authors also found a significant correlation between soluble ULBP-2 serum levels and ADAM10 expression in cancer cells from a cohort of pancreatic ductal adenocarcinoma patients." (PMID 32269567, 2020). "ULBP2 and MIC-1 have been reported to be overexpressed in various types of cancer tissue and to be secreted by cancer cells, including PC cells." (PMID 25295097, 2014). "Demonstrating the presence of soluble RAET1G2 protein in cancer patients is the obvious next step, however it will be technically challenging to produce specific antibodies as RAET1G2 is 95% identical to the ULBP2 molecule." (PMID 19223974, 2009). "UL-16 binding protein 2 (ULBP2), a human NKG2D ligand, has been identified as a poor prognostic factor in several cancers based on recent comprehensive analyses of immune-related genes using the Cancer Genome Atlas datasets." (PMID 40243581, 2025). "The ligands that bind to the NK-activating receptor NKG2D are ULBP1 and ULBP2/5/6, expressed at higher levels in cancer cells than in normal cells." (PMID 41050660, 2025). "Regarding the mechanisms involved in driving NK dysregulation in solid pediatric cancers, we showed that these patients did not have raised plasma levels of soluble ULBP2 or soluble MICA, both of which inhibit NK cell function in some adult cancer patients." (PMID 39310750, 2024). "Following selinexor incubation, we observed no significant change in the surface expression of ULBP-1, ULBP-2/5/6, MIC-A/B, CD54 (ICAM-1), B7-H6, or externalised calreticulin (ecto-reticulin), recently identified as the cancer associated ligand for NKp46." (PMID 37528310, 2023). "Our findings demonstrated that ULBP2 expressed on the surface of cancer cells promoted tumor growth by suppressing NK cell function, suggesting that modulating ULBP2-NKG2D interactions could be a potential target for cancer therapy." (PMID 40243581, 2025). "We also observed that ULBP2 expression is increased in HPV16-positive precancers as compared to HPV31-positive precancers, indicating that HPV16-positive precancers are more robust at evading immunosurveillance and, therefore more likely to progress to cancer than HPV31-positive precancers." (PMID 39672307, 2024). "Adding to the hypothesis that low expression of these ligands is a result of selective pressure by the immune system that results in cancer immune evasion or immunoediting, low expression of MIC-AB and ULBP-2 were prognostic factors for an unfavorable RFP of patients." (PMID 22257486, 2012).
cancer (continued). "Finally, by using the pCMVExt-Fc vector, we expressed two challenging proteins, the human ROR1-ED that is involved in cancer progression of a number of blood and solid malignancies and the ligand for the NKG2D activating receptor on the surface of NK cells, ULBP2." (PMID 29997597, 2018). "MICB, ULBP-1, and ULBP-2, but not MICA and ULBP-3, were detected in sera from most patients starting HD, and it was difficult to discriminate between the presence and absence of a cancer history using the levels of soluble NKG2DLs." (PMID 37674990, 2022).